BTG2 (BTG anti-proliferation factor 2)
Diseases named in the same sentence as BTG2 in open-access papers (continued):
Sharing a sentence is not in itself a finding about the gene and the disease.
cervical cancer (3 papers, 2022 to 2024). A primary or metastatic malignant neoplasm involving the cervix. "Recent studies suggest that BTG2 can block the Wnt/β-catenin signaling pathway, thus inhibiting cervical cancer cell growth." (PMID 39334363, 2024). "A cell cycle regulator protein BTG-2 is another target of microRNA-21 in cervical cancer progression." (PMID 35895593, 2022). "This implies that LINC01089 might influence cervical cancer through miR-27a-3p and BTG2, potentially affecting the Wnt/β-catenin signaling pathway." (PMID 39334363, 2024). "Similarly, in cervical cancer, LINC01089 also acts as a tumor suppressor by sponging miR-27a-3p to increase the expression of BTG2, thereby inhibiting cell proliferation and metastasis." (PMID 39334363, 2024).
follicular lymphoma (3 papers, 2019 to 2022). Follicular lymphoma is a form of non-Hodgkin lymphoma characterized by a proliferation of B cells whose nodular structure of follicular architecture is preserved. "Mutations in CREBBP, TNFRSF14 and KMT2D predominated in follicular lymphoma, whereas those in BTG2, HTA-A and PIM1 were more frequent in diffuse large B-cell lymphoma." (PMID 33945543, 2021). "Of these, mutations in CREBBP, KMT2D, TNFRSF14 and RRAGC were enriched in follicular lymphoma, and those of BTG2, HLA-A, PIM1, IGLL5, SOCS1, CD83 and SGK1 were enriched in DLBCL." (PMID 33945543, 2021). "As expected, mutations in frequent drivers such as CREBBP, KMT2D,TNFRSF14 and RRAGC were more frequent among follicular lymphomas, those of MYC, CCND3 and ID3 prevailed among Burkitt lymphoma and those of BTG2, PIM1, SGK1 and SOCS1 were more frequent among DLBCL." (PMID 33945543, 2021).
laryngeal carcinoma (3 papers, 2011 to 2021). Carcinoma that arises from the laryngeal epithelium. "Liu et.al discovered that miR-21 enhances the proliferation and suppresses the apoptosis of laryngeal cancer cells via targeting and downregulating BTG2." (PMID 34861847, 2021). "Recent studies have demonstrated that BTG2 is a new target gene of miR-21 in prostate cancer cells, laryngeal cancer cells and melanoma cells." (PMID 26132560, 2015). "Moreover, the regulation of BTG2 by miR-21 has been reported in human laryngeal carcinoma." (PMID 26132560, 2015).
lymph node metastasis (3 papers, 2025). "Conversely, infusion of mast cells overexpressing BTG2 improved chemotherapy efficacy and reduced lymph node metastasis." (PMID 40313959, 2025). "A subsequent investigation of associations demonstrated that UGCG and TNFRSF21 expression levels showed a positive relationship with NAC, whereas the expression of BTG2 and MYB, as well as the lymph node metastasis, were negatively correlated with the efficacy of NAC." (PMID 40332226, 2025). "The chi-square test and Fisher’s exact test indicated that postoperative RCB classification demonstrated a statistically significant correlation with the expression levels of UGCG, BTG2, TNFRSF21, and MYB, as well as lymph node metastasis in BRCA patients prior to NAC." (PMID 40332226, 2025). "Specifically, patients were more likely to achieve a higher RCB classification when they were negative for UGCG and TNFRSF21, but positive for BTG2 and MYB, with no lymph node metastasis." (PMID 40332226, 2025).
Nephropathy (3 papers, 2021 to 2024). A nonspecific term referring to disease or damage of the kidneys. "Consistently, we employed Nephroseq V5 online nephropathy database and found a lower expression of BTG2 in DKD than that in normal, with a statistical significance." (PMID 38831322, 2024). "We first examined TGF‐β1 expression in ADR‐induced FSGS and found that a massive Smad3 activation (phosphorylation) was evidenced in the glomeruli of ADR‐induced nephropathy, which was blocked by podocyte‐specific Btg2 knockout." (PMID 37749872, 2023). "Knockout studies suggest a protective role for Cdkn1a in kidney disease and Btg2 expression was also shown to be increased in the ischemic, but not contralateral control, kidney." (PMID 33946347, 2021).
pancreatitis (3 papers, 2020 to 2022). Inflammation of the pancreas. "BTG2‐positive level was lower in PC tissues than in pancreatic tissues obtained from patients with pancreatitis (P < .05)." (PMID 31724333, 2020).
pterygium (3 papers, 2009 to 2024). A wedge-shaped fibrovascular lesion arising from the bulbar conjunctiva and extending to the cornea. "The SVM algorithm was also employed to rigorously select hub genes associated with pterygium, revealing five significant genes: KRT10, KRT6B, BTG2, ASPG and NGEF." (PMID 39722894, 2024).
schizophrenia (3 papers, 2022 to 2023). A major psychotic disorder characterized by abnormalities in the perception or expression of reality. "In order to further explore the diagnostic value of the four hub genes (NFKBIA, CDKN1A, BTG2, and GADD45B) for schizophrenia, this experiment used ROC curves for evaluation." (PMID 35741729, 2022). "In conclusion, NFKBIA, CDKN1A, BTG2, GADD45B, and the joint indicators of four hub genes have great potential as biomarkers and therapeutic targets for the diagnosis of schizophrenia." (PMID 35741729, 2022). "Based on bioinformatics methods, this is the first study that found four hub genes closely related to schizophrenia (NFKBIA, CDKN1A, BTG2, and GADD45B)." (PMID 35741729, 2022).
thyroid cancer (3 papers, 2017 to 2023). "In clinical samples of patients with breast and thyroid cancer, decreased TOB1 is frequently detected, as well as BTG2 is reduced in breast and kidney cancer." (PMID 28922388, 2017).
acute pancreatitis (2 papers, 2022 to 2023). An acute inflammatory process that leads to necrosis of the pancreatic parenchyma. "Three targeted genes, Btg2, Zbp1, and Cd44, indirectly support the association between PAITA and tRF3-Thr-AGT in the mechanisms underlying acute pancreatitis initiation." (PMID 35045793, 2022).
asthma (2 papers, 2022 to 2024). "In a mouse model of asthma, EZH2 promoted asthma development through the FOXO3-miR-34b-BTG2 axis." (PMID 39108751, 2024).
brain cancer (2 papers, 2017 to 2026). A primary or metastatic malignant neoplasm affecting the brain. "With respect to brain cancer, increased TOB1-2 and BTG3 revealed poor prognosis, while higher BTG2 was related to better prognosis." (PMID 28922388, 2017).
colon cancer (2 papers, 2020 to 2023). "Our data also found that the expression of BTG4 is downregulated in lung and colon cancers, and overexpression of BTG4 can inhibit proliferation and migration, and induce apoptosis, suggesting that similar to BTG2 and BTG3, BTG4 might also act as a potential tumor suppressor." (PMID 32093041, 2020).
COVID-19 (2 papers, 2022 to 2025). A disease caused by infection with severe acute respiratory syndrome coronavirus 2. "Neutrophil transcripts which are robustly expressed in the uninfected state, including anti-proliferation and pro-apoptotic genes (LST1, G0S2, CPPED1, BTG2, PMAIP1) and anti-inflammatory genes (AMPD2, SEC14L1, ZFP36), are significantly downregulated in COVID-19 patients." (PMID 36466858, 2022).
invasive breast carcinoma (2 papers, 2014 to 2017). A carcinoma that infiltrates the breast parenchyma. "Several databases including TCGA and Sorlie, indicated a lower expression level of BTG2 in ductal and invasive breast cancer." (PMID 28922388, 2017).
leukemia (2 papers, 2006 to 2021). A malignant (clonal) hematologic disorder, involving hematopoietic stem cells and characterized by the presence of primitive or atypical myeloid or lymphoid cells in the bone marrow and the blood. "Constitutively active BTG2 in human leukemia U937 cells, induces G2/M cell cycle arrest by inhibiting the formation of the cyclin B1 and Cdc2 complex, thereby inhibiting the active kinase function of the complex." (PMID 16611356, 2006). "We previously demonstrated that miR-15a-5p decreased apoptosis induced by DNR and/or cytarabine in leukemia by downregulating three pro-apoptotic target genes—PDCD4, ARL2, and BTG2—validating the implication of miR-15a-5p in drug resistance." (PMID 34068078, 2021).
metastatic cancer (2 papers, 2019 to 2020). A carcinoma which has spread from the original site of growth to another anatomic site. "MRNAs PRKCD, PRKAR1A, BTG2 competed with lncRNA RP11-408O19.5 for the same miRNAs (miR-15a-5p, miR-15b-5p, miR-16-5p, miR-195-5p) in primary cancer; lncRNA RP11-408O19.5 competed with GGA3 for miR-15b-5p, miR-16-5p, and miR-195-5p in metastatic cancer." (PMID 33614509, 2020). "Altogether, the present study support our hypothesis that BTG2/TIS21 is a promising target to combat with metastatic cancers with high level of Twist1 without BTG2/TIS21 expression." (PMID 31138781, 2019).
myocardial infarction (2 papers, 2022 to 2023). Gross necrosis of the myocardium, as a result of interruption of the blood supply to the area, as in coronary thrombosis. "BTG2 was found to be up-regulated under OGD conditions, which suggests that BTG2 plays an important role in myocardial infarction." (PMID 35870960, 2022).
myopia (2 papers, 2024 to 2025). "Our results indicate that BTG2-mediated apoptosis and retinal damage may be a potential target in the treatment of myopia." (PMID 38807184, 2024). "To investigate the role of BTG2 signaling-related molecules in the retina in the development of myopia, we established the lens-induced myopia (LIM) model in guinea pigs, and then supplemented miR-92b-3p-carrying lentivirus (intravitreal injection) in experimental myopic eyes." (PMID 38807184, 2024). "Firstly, we did not knock down the BTG2 gene to observe the effect of the lack of BTG2 on DNA damage- and apoptosis-related genes as well as the development of myopia." (PMID 38807184, 2024).
renal cell carcinoma (2 papers, 2019 to 2022). "In this study, we confirm that BTG2 is frequently down-regulated in renal cell carcinoma (RCC) tissues and its low expression is associated with unfavorable prognosis and decreased m6A level." (PMID 36591524, 2022). "Another study also reported low levels of BTG2 expression in renal cell carcinoma." (PMID 36591524, 2022). "Additionally, BTG2 was downregulated in renal cell carcinoma as compared to normal control renal tissue, whereas BTG2 overexpression was associated with inhibition of cell growth, migration, and invasion." (PMID 31223310, 2019).
sarcopenia (2 papers, 2024). Progressive decline in muscle mass due to aging which results in decreased functional capacity of muscles. "The highlight of our study is the identification of six potential diagnostic markers for sarcopenia: BTG2, FOXO3, AQP9, SCN1B, CYCS, and GPC3." (PMID 39777262, 2024). "Specifically, in the sarcopenia dataset, the CEBPB showed the best diagnostic efficiency for differentiating sarcopenia, while BTG2, CDKN1A, CEBPB, DDIT4, and NFKBIA showed the best-differentiating capability in the OA dataset." (PMID 38962732, 2024). "Six biomarkers—BTG2, FOXO3, AQP9, GPC3, CYCS, and SCN1B—were identified alongside a diagnostic model that offers a novel approach for early diagnosis of sarcopenia." (PMID 39777262, 2024). "In the sarcopenia dataset, BTG2 (AUC = 0.867), CDKN1A (AUC = 0.892), CEBPB (AUC = 0.942), DDIT4 (AUC = 0.792), FOXO3 (AUC = 0.900), NFKBIA (AUC = 0.892), ZBTB16 (AUC = 0.808) and ZFP36 (AUC = 0.775) demonstrated better diagnostic efficacy in distinguishing sarcopenia patients from healthy controls." (PMID 38962732, 2024).
allergies (1 paper, 2025). "Our preliminary data suggest a correlation between tryptase levels and BTG2 expression in tumor tissues and in mast cells, but the serum tryptase specificity is limited by non-neoplastic conditions such as allergies." (PMID 40313959, 2025).
anxiety depression (1 paper, 2024). "Six core mRNAs on which ZZCD works for anxiety depression were obtained by constructing PPI network: Fos, Junb, Egr2, Dusp1, Nr4a1, and Btg2." (PMID 37905694, 2024).
calcific aortic valve disease (1 paper, 2024). "Despite these insights, the role of BTG2 in calcific aortic valve disease (CAVD) remains unexplored." (PMID 39749331, 2024).
cervical (1 paper, 2022). "Furthermore, microRNA‐21 affects other direct target molecules including PDCD-4, TPM-1, FASL, and BTG-2 in order to stimulate its cervical carcinogenesis effect." (PMID 35895593, 2022).
chronic lymphocytic leukemia (1 paper, 2025). "BTG2 was reported to be involved in the Richter transformation in chronic lymphocytic leukemia and was considered to be one of the molecular labels to classify DLBCL." (PMID 39811936, 2025).
clear cell renal cell carcinoma (1 paper, 2017). "As for clear cell renal cell carcinoma, which account for the majority of kidney cancer, BTG2 and BTG4 were reduced, while BTG1 was elevated in clear cell renal cell carcinoma compared with normal kidney tissue group." (PMID 28922388, 2017).
esophageal squamous cell carcinoma (1 paper, 2025). Esophageal squamous cell carcinoma (ESCC) is a type of esophageal carcinoma (EC) that can affect any part of the esophagus, but is usually located in the upper or middle third. "Recent study has reported that the carcinogenic mechanism of NOX2 in esophageal squamous cell carcinoma (ESCC) may be associated with the regulation of B-cell translocation gene 2 (BTG2)." (PMID 41441930, 2025).
Glomerular sclerosis (1 paper, 2023). Accumulation of scar tissue within the glomerulus. "Furthermore, ADR‐induced albuminuria, glomerular sclerosis, and mesangial expansion in Btg2+/− mice were also inhibited in Btg2KO mice." (PMID 37749872, 2023).
glomerulosclerosis (1 paper, 2023). A hardening of the kidney glomerulus caused by scarring of the blood vessels. "Podocyte‐specific deletion of Btg2 protected against the onset of proteinuria and glomerulosclerosis in ADR‐treated mice along with inhibition of EMT markers such as α‐SMA and vimentin while restoring epithelial marker E‐cadherin." (PMID 37749872, 2023).
infarction (1 paper, 2022). A localised pathological necrosis of tissue resulting from obstruction of the blood supply usually by a thrombus, an embolus, or vascular torsion. "In vivo experiments showed that both IFN-γ-Exo and Ctrl-Exo could down-regulate the expression of BTG2 in myocardial tissue after infarction, and IFN-γ-Exo had a better inhibitory effect." (PMID 35870960, 2022).
lymphocytic leukemia (1 paper, 2026). "PC3/Tis21/BTG2 and BTG1, prototype members of the BTG/Tob family, are antiproliferative transcriptional cofactors discovered 35 years ago as genes induced by nerve growth factor and phorbol 12-myristate 13-acetate or associated with lymphocytic leukemia." (PMID 42080092, 2026).
metastasis (1 paper, 2020). The spread or migration of cancer cells from one part of the body (where they first appeared) to another. "The expression of miR‐27a and BTG2 was found to be correlated with differentiation, tumour node metastasis (TNM) stage and lymph node metastasis in PC patients (P < .05)." (PMID 31724333, 2020).
morbid obesity (1 paper, 2021). An excess of body weight, normally defined as an individual with a body mass index greater than 35 or a body weight greater than one hundred percent of ideal body weight. "The difference in expression of Btg2 and Cdkn1a in the mice fed the WD and AD suggest morbid obesity and nutritional inadequacies influence the pathophysiology of kidney injury via different cellular mechanisms and may have different long-term outcomes." (PMID 33946347, 2021).
neuropathy (1 paper, 2025). A disorder affecting the nervous system that manifests with pain, tingling, numbness, and/or muscle weakness. "Additionally, one other variant, the rs6682221 variant of the anti-proliferation factor 2 (BTG2) gene, appeared to have a protective effect, reducing the risk of neuropathy to approximately 0.045." (PMID 40650017, 2025).
oligodendroglioma (1 paper, 2012). A well-differentiated (WHO grade II), diffusely infiltrating neuroglial tumor, typically located in the cerebral hemispheres. "Here we examined the effects of Btg2 downregulation and overexpression on the tumorigenicity of PDGF-induced oligodendrogliomas." (PMID 23203087, 2012).
oral squamous cell carcinoma (1 paper, 2020). "Similarly, EGCG was found to suppress cell proliferation by upregulating BTG2 (B-cell translocation gene 2) expression via MAPK pathway in oral squamous cell carcinoma (OSCC), in particular with the phosphorylation of p38, JNK, and ERK." (PMID 31979082, 2020).